PDK4 (pyruvate dehydrogenase kinase 4)
Description:
Kinase that plays a key role in regulation of glucose and fatty acid metabolism and homeostasis via phosphorylation of the pyruvate dehydrogenase subunits PDHA1 and PDHA2. This inhibits pyruvate dehydrogenase activity, and thereby regulates metabolite flux through the tricarboxylic acid cycle, down-regulates aerobic respiration and inhibits the formation of acetyl-coenzyme A from pyruvate. Inhibition of pyruvate dehydrogenase decreases glucose utilization and increases fat metabolism in response to prolonged fasting and starvation. Plays an important role in maintaining normal blood glucose levels under starvation, and is involved in the insulin signaling cascade. Via its regulation of pyruvate dehydrogenase activity, plays an important role in maintaining normal blood pH and in preventing the accumulation of ketone bodies under starvation. In the fed state, mediates cellular responses to glucose levels and to a high-fat diet. Regulates both fatty acid oxidation and de novo fatty acid biosynthesis. Plays a role in the generation of reactive oxygen species. Protects detached epithelial cells against anoikis. Plays a role in cell proliferation via its role in regulating carbohydrate and fatty acid metabolism.
Tractability: Small molecule: an approved drug acts on it; a structure with a bound ligand is known; a high-quality ligand is known; it has a high-quality binding pocket. PROTAC: ubiquitination databases record sites on it; a small molecule that binds it is known.
Target class: Kinase; Enzyme; Atypical protein kinase PDHK subfamily; Atypical protein kinase group; Protein Kinase
Gene: Protein-coding gene on chromosome 7 (95,583,497 to 95,597,638, reverse strand). Ensembl gene ENSG00000004799.
Subcellular location: Mitochondrion matrix
Pathways (Reactome):
Gene expression (Transcription): MLL4 and MLL3 complexes regulate expression of PPARG target genes in adipogenesis and hepatic steatosis
Metabolism: Regulation of pyruvate dehydrogenase (PDH) complex
Signal Transduction: Signaling by Retinoic Acid
Gene Ontology:
Molecular function: ATP binding; protein binding; protein kinase activity; pyruvate dehydrogenase (acetyl-transferring) kinase activity
Biological process: cellular response to fatty acid; cellular response to starvation; regulation of fatty acid biosynthetic process; regulation of pyruvate decarboxylation to acetyl-CoA; glucose homeostasis; insulin receptor signaling pathway; regulation of fatty acid oxidation; regulation of glucose metabolic process; regulation of ketone metabolic process; regulation of pH; response to starvation; cellular response to stress; regulation of bone resorption
Cellular component: mitochondrion; mitochondrial matrix
Genetic constraint (gnomAD): Loss-of-function variants: 9 observed, 12.62 expected, observed/expected ratio (o/e) 0.71, 90% interval 0.43 to 1.24. The upper end of that interval is the gene's LOEUF score, 1.24, which puts it in group 5 of 6, group 1 being the genes least tolerant of losing a copy. Missense variants: 189 observed, 190.86 expected, observed/expected ratio (o/e) 0.99, 90% interval 0.88 to 1.12. Synonymous variants: 72 observed, 68.53 expected, observed/expected ratio (o/e) 1.05, 90% interval 0.87 to 1.28.
Homologues: Orthologues: chimpanzee PDK4 (99% identical), macaque PDK4 (98% identical), rabbit PDK4 (96% identical), dog PDK4 (93% identical), mouse Pdk4 (93% identical), guinea pig PDK4 (93% identical), pig PDK4 (92% identical), rat Pdk4 (91% identical), tropical clawed frog pdk4 (72% identical), zebrafish pdk4 (71% identical), Drosophila melanogaster Pdk (52% identical), Caenorhabditis elegans pdhk-2 (49% identical). Paralogues in human: PDK1 (65% identical), PDK2 (64% identical), PDK3 (61% identical), BCKDK (27% identical).
Diseases named in the same sentence as PDK4 in open-access papers:
PDK4 is named in the same sentence as 176 diseases in open-access papers, as found by Europe PMC text mining. Sharing a sentence is not in itself a finding about the gene and the disease. The quoted sentences say what the papers report.
diabetes (64 papers, 2006 to 2025). "As such, heightened Pdk4 expression has been linked to conditions associated with muscle atrophy, including animal models of diabetes, cancer cachexia, sepsis, statin-induced myopathy and amyotrophic lateral sclerosis." (PMID 39940943, 2025). "In particular, expression of PDK4, which has been linked to diabetes and glucose metabolism previously, shows a high correlation with GIR and FG in muscle but almost none in IMAT." (PMID 36790478, 2023). "Pyruvate dehydrogenase kinase 4, encoded by PDK4, plays an important role in glucose metabolism and oxidation of fatty acids, and its upregulation is a factor in developing diabetes." (PMID 38137029, 2023). "Previously, some reports revealed that PDK4 have shown a close association with diabetes, heart disease, and carcinomas." (PMID 34220962, 2021). "Cumulative evidence has shown that the up-regulation of PDK4 expression is tightly associated with obesity and diabetes." (PMID 29656110, 2018). "PDK4 was first identified in a linkage study of loci associated with Type 2 diabetes mellitus in Native Americans, and insulin is known to repress PDK4 transcription." (PMID 26576332, 2015). "Accordingly, the expression of PDK4 is increased in fasting, diabetes and other conditions associated with switching from glucose oxidation to fatty acid oxidation." (PMID 22682013, 2012). "The expression of PDK4 is elevated by diabetes, fasting and other conditions associated with the switch from the utilization of glucose to fatty acids as an energy source." (PMID 22682013, 2012). "Elevated Pdk4 levels are associated with metabolic inflexibility and subsequent fat accumulation, marked by the muscle’s impaired ability to switch between fuel sources, often linked to diabetes and obesity." (PMID 39940943, 2025). "Functionally, PDK4 downregulation attenuated HG/HP‐induced hypertrophy, apoptosis, and oxidative damage in cardiomyocytes, highlighting the pathogenic role of Decr1 as a key mediator of diabetes‐induced cardiac injury." (PMID 40052435, 2025). "Previous studies have shown a close association between Pdk4 and diabetes and heart disease." (PMID 38961143, 2024). "Diabetes, fasting, and other conditions associated with the switch from the utilization of glucose to fatty acids as an energy source can up-regulate the expression of PDK4." (PMID 33739396, 2021). "Diseases associated with shifts from glucose to fatty acid utilization for energy production, such as diabetes and fasting states, also upregulate PDK4 expression." (PMID 39966707, 2025). "Pdk2 and Pdk4 double knockout mice with STZ-induced diabetes reveal the attenuated DPN pathogenesis via suppressing lactate-induced inflammation." (PMID 40429808, 2025). "During fasting and diabetes, PDK4 is widely upregulated in major tissues, in response to insulin depletion and increased glucocorticoids and free fatty acids." (PMID 39966707, 2025). "Increased activity of PDK4 in skeletal muscle inhibits glucose oxidation, thereby exacerbating blood glucose levels, and is therefore highly expressed in diabetes." (PMID 38671369, 2024). "Among the top upregulated genes in response to HFD/STZ-induced diabetes within each cell population were transcripts for Pdk4, Angptl4, Txnip, Postn, Hmgcs2, and Ucp3, of which several have been previously involved in heart failure." (PMID 37010266, 2023). "The PDK4 level is elevated in patients with diabetes, and a PDK inhibitor enhances insulin activity by promoting glucose oxidation." (PMID 38104056, 2023). "ERRα was indicated to inhibit skeletal muscle glucose catabolism by transcriptionally activating Pdk4, a negative regulator of glucose oxidation that is elevated in diabetes." (PMID 37802398, 2023). "To explore the possible mechanism of how high glucose affects prostate epithelial cells, we examined the expression of PDK4 in non-diabetes, diabetes BPH patients’ prostates, and in high glucose treated BPH-1 and RWPE-1 cells." (PMID 37863991, 2023).
diabetes (continued). "A total of 24 osteoporosis-related genes, including IGF1, IL6, pyruvate dehydrogenase kinase 4 (PDK4), PPARGC1A, and TF, were also associated with obesity and diabetes." (PMID 35328013, 2022). "In many studies of hypermetabolism-related diseases such as diabetes and liver injury, PDK4 was found to reduce oxidative stress and play a cytoprotective role." (PMID 36358433, 2022). "The results of the study showed that PDK4 gene expression in the endurance training group, diabetes+endurancetraining group, diabetes+endurance training+DCA group and endurance training+DCA group was higher compared tothe control group." (PMID 32347035, 2021). "Previous studies reported that pyruvate dehydrogenase kinase 4 (PDK4) is closely related to diabetes, heart disease, and carcinomas." (PMID 34220962, 2021). "Concerning glucose oxidation, the expression of the PDK4 protein, known to inhibit pyruvate conversion to acetylCoA, was increased by diabetes induction (+415% in general, p < 0.01)." (PMID 31690052, 2019). "Both PDK2 and PDK4 isoforms are attractive metabolic targets for pharmacological interventions to treat diabetes and obesity." (PMID 31712597, 2019). "For instance, PDK4 is involved in metabolic changes under high-fat diet condition and diabetes, while PDK1 and PDK3 are more likely to contribute to metabolic switch and cell survival under hypoxia." (PMID 31409724, 2019). "Other genes involved in obesity (e.g., Cidec, Cd36), diabetes (Igfbp1), inflammation (Cd63), mitochondrial function (Pdk4) and cancer (H19) were also upregulated by the soybean oil diet." (PMID 26200659, 2015). "Consistent with our findings are reports that PDK4 expression is increased in diabetics and that Pdk4-/- mice are resistant to HFD-induced hepatic steatosis and are more glucose tolerant." (PMID 26200659, 2015). "PDK4 expression has been shown to be regulated by various metabolic stimuli (such as starvation, exercise, and diabetes), the transcription factors FOXO and E2F1, and epigenetic mechanisms such as promoter methylation and histone acetylation." (PMID 25379179, 2014). "To further investigate the role of Pdk2 and Pdk4 in the pathogenesis of diabetes in the IrsLDKO mice, we deleted either the Pdk2 or Pdk4 gene on the IrsLDKO genetic background." (PMID 23940800, 2013). "In this study, we directly assessed the involvement of Pdk2 and Pdk4 in the pathogenesis of diabetes." (PMID 23940800, 2013). "To examine the specific hepatic effects of Pdks on diabetes, we also knocked down the Pdk2 or Pdk4 gene using specific shRNAs." (PMID 23940800, 2013). "PDK2 and PDK4 are both increased in conditions in which insulin levels are low (e.g., starvation and diabetes)." (PMID 23730261, 2012). "In mammals, PDK-4 appears to be important in controlling diabetes and obesity, and its expression at the mRNA and protein levels is regulated by seasonal changes in hibernating animals, which require tight control of fuel selection." (PMID 22848591, 2012). "Starvation and diabetes also markedly increased the abundance of PDK4 mRNA especially in muscle tissues." (PMID 16390543, 2006). "Notably, PDK4 exhibits elevated expression levels during periods of starvation and in cases of diabetes." (PMID 39877632, 2025). "However, upregulation of PDK4 and PDK1 expression has been linked to obesity and diabetes, respectively." (PMID 40868918, 2025). "Future studies could investigate whether targeting Pdk4, Slc25a20, or other metabolic regulators can restore substrate flexibility and improve coronary microvascular function in diabetes." (PMID 41203872, 2025). "Our previous studies showed that PDK4 inhibition by DCA protects against obesity-associated insulin resistance via regulation of adipose tissue inflammation, atherosclerosis, and diabetes." (PMID 39122684, 2024). "Interestingly, Pdk4 gene expression was increased in diabetes and decreased by dapagliflozin in both WT and diabetic animals." (PMID 36809274, 2023).
diabetes (continued). "IGFBP6 and PDK4 were upregulated in patients with diabetes and diabetes-related complications." (PMID 36276976, 2022). "The higher levels of ketogenic AAs are likely due to elevated pyruvate dehydrogenase kinase isoform 4 (PDK4) expression in patients with diabetes that interferes with the conversion of pyruvate to acetyl coenzyme A, leading to the conversion of ketone bodies to ketogenic AAs." (PMID 35456051, 2022). "Abnormal regulation of PDC in diabetes is associated with two isoforms: PDK2 and PDK4." (PMID 33739396, 2021). "The results of the study showed that PDK4 geneexpression was higher in the endurance training group(P=0.018), diabetes+endurance training group (P=0.008),diabetes+endurance training+DCA group (P=0.001) andendurance training+DCA group (P=0.026) compared tothe control group." (PMID 32347035, 2021). "Given that the PDK-4 inhibition is beneficial both in diabetes and vascular calcification, it is reasonable to assume that lowering the PDK-4 activity might have a dual positive effect on diabetic vascular calcification." (PMID 34502172, 2021). "Furthermore, pyruvate dehydrogenase kinase 4 (PDK4), an important metabolic regulator, is elevated in several atrophic conditions including cancer, starvation, diabetes, and sepsis." (PMID 32635462, 2020). "We also tested whether diabetes or treatment with NC, which may by itself affect hepatic PDK4 expression, induced PDK4 expression in our patient cohort." (PMID 30808993, 2019). "Moreover, the reduced expression of PDK4 shed a promising light on the therapeutic potential of Cl_Cr(III) since the elevated expression of PDK is characteristic of patients with diabetes, vascular calcification and heart failure." (PMID 29292726, 2017). "Since hyperactivation of PDK4 has been reported in calcified vessels and in patients with diabetes mellitus, inhibition of PDK4 expression may be a strategy for the prevention of diabetic vascular calcification." (PMID 29348870, 2017). "Thus PDK4 expression is also of interest in diabetes, since its up-regulation can contribute to hyperglycemia." (PMID 27332823, 2016). "Significant interaction effect of diabetes with DOX was observed in PDK4 (P = 0.019)." (PMID 27512375, 2016). "In conclusion, our data suggest that hepatic Pdk4 may be critically involved in the pathogenesis of diabetes." (PMID 23940800, 2013). "In summary, hepatic Pdk4 gene expression is highly induced in diabetes." (PMID 23940800, 2013). "UCP3, MCAD and PDK4 are peroxisome proliferator-activated receptor α (PPARα) targets, a transcription factor that is activated by fatty acid ligands to upregulate fat metabolism, and is increased in diabetes." (PMID 24063408, 2013). "Moreover, Pdk4 gene expression is often induced in the liver and skeletal muscle under insulin resistance and diabetes conditions." (PMID 23940800, 2013). "The herein reported induction of Pdk4 expression in the skeletal and heart muscle might represent a novel mechanism involved in the development of diabetes mellitus in HH." (PMID 17949489, 2007). "Additionally, downregulation of PDK4 curbed the protein expression of β‐MyHc, IL‐1β, and cleaved caspase‐3 in HG/HP‐incubated cardiomyocytes, suggesting that PDK4 may be a driver for diabetes‐induced cardiac hypertrophy, apoptosis and oxidative damage." (PMID 40052435, 2025). "Additionally, diabetes-related BPH patients had reduced PDK4 expression." (PMID 37863991, 2023). "Therefore, it is in our best interest into investigating whether ecARNT in diabetes would regulate the production of ROS resulting from the upregulation of OXPHOS via a novel PDK4 dependent pathway or through the same pathway regulated by PDK1 above." (PMID 34179020, 2021). "Besides, the PDK4 expression was increased by peroxisome proliferator-activated receptor-a (PPARa) and WY-14,643 (a potent agonist for PPARa receptor) in starvation and diabetes." (PMID 30554191, 2018).
diabetes (continued). "Thus while regulation of PDK1-3 reflects the immediate energy demands of the cell, PDK4 is reflective of whole organism energy balance and is upregulated in metabolic conditions such as hibernation, sustained exercise, and diabetes." (PMID 26576332, 2015). "Thus Pdk4 upregulation may be a contributing factor to both lipid accumulation in the liver and the development of diabetes and glucose intolerance in SO-HFD mice." (PMID 26200659, 2015). "Thus, the inactivation of PDC that occurs in most of the major tissues of the body during starvation and diabetes is likely explained by the effects that a decrease in insulin and an increase in glucocorticoids and FFAs have on PDK4 expression under these conditions." (PMID 23730261, 2012). "To further understand the involvement of hypercholesterolemia in diabetes, we measured expression of genes, CPT1, and PDK4, related to fatty acid oxidation." (PMID 36829889, 2023). "In starvation and diabetes, nutritional factors and hormones regulate the expression of PDK2 and PDK4, and the body reduces the activity of PDC by increasing PDK activity." (PMID 33739396, 2021). "But following inhibitionof PDK4 in the cardiac muscle using DCA, expressionof PGC-1α decreased in endurance training+DCA group,the endurance training+diabetes+DCA group, and thediabetes+DCA group." (PMID 32347035, 2021). "Remarkable up-regulation of PDK4 has been reported in humans with Type 2 diabetes, in spontaneously diabetic Otsuka Long-Evans Tokushima Fatty (OLETF) rat diabetes, in animals and humans fed a high fat diet." (PMID 33739396, 2021). "The C/C cells showed differential binding affinity compared to C/T cells in some previously identified TCF7L2 target genes that are involved in diabetes, such as ACSL5, ATM, AKT2, LEF1, and PDK4." (PMID 32651957, 2020). "E2F1 transcriptional activation of the pyruvate dehydrogenase kinase 4 (PDK4) gene, a key nutrient sensor that is constitutively expressed in diabetes, was also demonstrated to regulate glucose homeostasis in muscle through inhibition of glucose oxidation." (PMID 23355973, 2013). "Aberrant regulation of PDC in diabetes involves two isoforms: PDK2 and PDK4." (PMID 39966707, 2025). "Increased expression of Sorbs3 (p = 5.5 × 10–18), Ptpre (p = 0.006) and decreased expression of Pdk4 (p = 0.048) and Dnmt3b (p = 1.2 × 10–11) in VSG GK rats further support the involvement of epigenetic mechanisms in diabetes remission and in the long-term adaptation to bariatric surgery." (PMID 41360887, 2025). "Western blot validation of several proteins with high pathophysiological importance, including MYH7, HMGCS2, PDK4, and BDH1, indicated that mass spectrometry was able to qualitatively, but not quantitatively, reflect the fold changes of certain proteins in diabetes." (PMID 39539089, 2024). "It is also noticed that Pdk4 gene expression is highly induced in the liver of the IrsLDKO mice due to the impairment of insulin signaling; however, it is not clear that, to what extent, the elevated Pdk4 contributes to the diabetes in the IrsLDKO mice." (PMID 23940800, 2013). "We examined the expression of PDK4 in non-diabetes and diabetes BPH patients (n = 3/group) prostate epithelial cells of transition zone by immunohistochemical staining, and we found that compare with non-diabetes patients, the expression of PDK4 lower in diabetes patients." (PMID 37863991, 2023). "Third, we could not evaluate whether repression of PDK4 expression by miR-148a-3p had a direct effect on erection in diabetes-induced ED." (PMID 38104056, 2023). "Unlike the roles of PDK2 and PDK4, the role of PDK1 is underexplored in obesity and diabetes." (PMID 34552205, 2021).